MMP9 (matrix metallopeptidase 9)
Diseases named in the same sentence as MMP9 in open-access papers (continued):
Sharing a sentence is not in itself a finding about the gene and the disease.
atherosclerosis (continued). "Immunohistochemical analysis showed positive staining and significantly increased expression of NF-ĸB, VCAM1 and MMP9 proteins in the atherosclerosis group compared to the NC group (P < 0.05, P < 0.01)." (PMID 32213192, 2020). "NF-κB signaling has been shown to contribute to development of atherosclerosis and the formation of unstable plaques through enhanced inflammatory cytokine production and matrix metallopeptidase 9 (MMP-9) expression." (PMID 31769428, 2019). "MMP-9 levels are increased in a number of cardiovascular diseases, including hypertension, atherosclerosis, and myocardial infarction." (PMID 31578449, 2019). "Foamy macrophages are known to produce MMP9 and cathepsin K in diseases including atherosclerosis, and MMP9 in multiple sclerosis." (PMID 31736973, 2019). "To further elucidate the contribution of NAP9 in the protection against atherosclerosis, we analyzed the levels of MMP-9, indicative of EMMPRIN activation in carotid arteries." (PMID 30347750, 2018). "Our results verified that TNF-α administration substantially increased the levels of inflammatory cytokines, such as interleukins, MCP-1, MMP-2, and MMP-9, that mainly contribute to the development of vessel dysfunction in atherosclerosis." (PMID 30577658, 2018). "These discovered roles of MMP-9 provide countless options for novel therapeutic targets in the treatment of pathological conditions including cancer, atherosclerosis, diabetes, inflammation, and wound healing." (PMID 30149671, 2018). "While not directly regulating smooth muscle cells, LXR-mediated repression of NFκB-induced expression of Mmp-9, reduces degradation of the extracellular matrix secreted by smooth muscle cells that allow for plaque stability in later stage atherosclerosis." (PMID 30087224, 2018). "The current study data from animal experiment, observation of circulating markers and expression investigations on atherosclerotic tissue, has indicated a role of MMP-9 in atherosclerosis." (PMID 29507703, 2018). "Recent knock-out study also suggests that MMP2 and MMP9 are crucial in development of arterial lesions resulting in atherosclerosis." (PMID 30046331, 2018). "MMP9 has been considered a major pathological factor in atherosclerosis due to its significant role in migration and proliferation of smooth muscle cells during plaque formation." (PMID 30115989, 2018). "LXR-dependent repression of Mmp-9 within macrophages prevents the advancement of atherosclerosis through promoting plaque stabilization by preventing degradation of the fibrous cap." (PMID 30087224, 2018). "While it is reassuring that the final selection includes established mediators of ECM degeneration like MMP9, omics analyses provide a more integrated assessment of the molecular signature in symptomatic atherosclerosis." (PMID 28319050, 2017). "Increases of plasma MMP-9 are involved in the pathogenesis of early atherosclerosis and hypertension, and are probably one of the initiative factors of progressing arterial stiffness." (PMID 28876367, 2017). "It should be emphasized that our novel observations advocate the activation/cleavage of PAR-1 by MMP-9 in atherosclerosis." (PMID 28166283, 2017). "They found a higher amount of MMP9 in comparison to their expression in atherosclerosis, which demonstrates their involvement in extracellular matrix degradation, smooth muscle cell apoptosis, renin-angiotensin system activity, and neovascularization." (PMID 29158612, 2017). "According to MMPs involvement in atherosclerosis, the MMP9 content and gelatinolytic activities were higher in extracts from PL tissues than in those from non-atherosclerotic arteries." (PMID 28687781, 2017). "The animal experiments have discovered that the atherosclerosis lesions and VSMCs intima migration in the MMP-9 gene knock-out mice were remarkably decreased than that in the wild-type mice." (PMID 27375491, 2016).
atherosclerosis (continued). "Levels of proteins (osteoprotegerin, osteopontin, osteocalcin, matrix γ-carboxyglutamic acid protein, fetuin A, MMP-2, MMP-9, TIMP-1, TIMP-2) and biochemical parameters were measured to analyse their influence on atherosclerosis risk in CKD patients." (PMID 26843213, 2016). "MMP-9 induces atherosclerotic plaque rupture, and its expression is strongly correlated with lesion instability and the manifestation of atherosclerosis." (PMID 27314393, 2016). "For atherosclerosis event, MMP-9 and MMP-2 play key role by degrading ECM and facilitating VSMC migration from media to intima of blood vessel." (PMID 27066292, 2016). "Significantly higher serum concentrations of MMP-2 and MMP-9 are found in patients with T2D and atherosclerosis." (PMID 27490532, 2016). "This atherosclerosis improvement was found to be due, at least in part, to downregulation of inflammation state by increasing serum adiponectin and decreasing MMP-9." (PMID 26965176, 2016). "MMP-9 (also known as gelatinase B) is one the most extensively researched MMPs and exhibits enhanced expression in atherosclerosis injury sites." (PMID 27375491, 2016). "Vascular inflammation is recognized as the foundation mechanism of atherosclerosis, and proinflammatory mediators including IL-6, TNF-α, and MMP-9 play a pivotal role in atherosclerosis." (PMID 27403152, 2016). "Studies on lipid uptake in atherosclerosis models have reported increased expressions of matrix metalloproteinase 9 (MMP9) in cyclophilin A mediated foam cell formation." (PMID 27809851, 2016). "The study data also suggest that that factors mediating relationship between cardiometabolic syndrome, chronic kidney disease, and atherosclerosis can include malondialdehyde and MMP-9." (PMID 26538831, 2015). "The expressions of MMP-2 and MMP-9 in atherosclerosis are regulated via various pathways, such as p38 mitogen activated protein kinase (MAPK), extracellular signal regulated kinase 1 and 2 (ERK1/2), Akt, and nuclear factor kappa (NF-κB)." (PMID 26690114, 2015). "Evidence shows that matrix metalloproteinase (MMP)-2 and MMP-9 are related to the pathogenesis of atherosclerosis." (PMID 26690114, 2015). "In human atherosclerosis, it is believed that the increased activity of matrix metalloproteinase 9 (MMP-9) can lead to the upregulation of collagen deposition, possibly through transforming growth factor-β activation." (PMID 26622476, 2015). "Both MMP9 and CCL2 are associated with atherosclerosis where CCL2 attracts monocytes that mature into macrophages and produce MMP9." (PMID 25978399, 2015). "Since monocytes and T cells constitute the major infiltrating cell types in atherosclerosis, we compared the expression of MMP-9 (and TIMP-1) in monocytes and T cells by using flow cytometry." (PMID 25153995, 2014). "All of these results were confirmed using confocal microscopy, where the effects of the treatment with EAH highly reduced the expression of MMP-9, which is at the end stage of atherosclerosis." (PMID 24891839, 2014). "MMP9 was potentially important in the development of atherosclerosis in a Malaysian study population." (PMID 25318463, 2014). "Atherosclerosis shares several characterstics with a chronic inflammatory process and MMP-9 is considered to play a key role in disease progression and vulnerability to plaque rupture." (PMID 25153995, 2014). "The immuohistochemical staining of atherosclerosis was performed to detect the expressions of MMP-9 and LOX-1." (PMID 25007151, 2014). "Apart from MMP-2, the role of MMP-9 in the pathogenesis of vascular changes in atherosclerosis has also been established." (PMID 25145866, 2014). "Various cytokines induced in vascular injury and immunoinflammatory responses contribute to atherosclerosis and restenosis through MMP-9 mediated VSMC migration." (PMID 23840100, 2013).
atherosclerosis (continued). "Studies to elucidate the pathogenic molecular mechanism of Lcn2 in atherosclerosis and CAD have shown that the Lcn2/MMP-9 complex acts to destabilize the artery plaque." (PMID 24359145, 2013). "Another promising candidate widely investigated in observational studies in atherosclerosis is represented by MMP-9." (PMID 23365489, 2013). "Chronic hypoxia also accelerates the development of atherosclerosis along with activated MMP-9 in apoE(−/−) mice." (PMID 23840100, 2013). "MMP-9 alone, however, has been suggested to promote atherosclerosis by degrading the vascular basement membrane, thereby increasing endothelial permeability and allowing more white blood cells and inflammatory cytokines to infiltrate the intima." (PMID 24359145, 2013). "Several genetic association studies on the role of specific MMP variants in atherosclerosis have been performed, especially with MMP1, MMP-3, and MMP-9." (PMID 23365489, 2013). "Because plaque composition, rather than size, determines the clinical course and consequences of atherosclerosis, the main plaque cellular components, macrophages, MMP-9, SMCs and collagen content were studied." (PMID 24146955, 2013). "Some in vitro research reported that inhibition of both cell proliferation and MMP-9 activity has appeared by various oriental herbs, which is used for the treatment of atherosclerosis." (PMID 24159354, 2013). "In our study we found that high fructose diet enhanced expression of MMP-9, a gelatinase enzyme, in atheroma-free area of the vessels during early stages of atherosclerosis development." (PMID 22474431, 2012). "Recent studies have shown that gelatinase B also known as matrix metalloproteinase-9 (MMP-9), an endopeptidase capable of degrading the extracellular matrix, is thought to be associated with atherosclerosis, and plaque rupture." (PMID 22988542, 2012). "It has been recently demonstrated that down-regulation of MMP-9 via insulin treatment will result in reduction of intimal lesions in atherosclerosis-prone diabetic apoE (-/-) mice." (PMID 22114787, 2011). "In cardiovascular illness, carrying of the T allele and/or higher MMP9 levels are related to an increased progression and mortality of coronary heart disease (CHD) increased atherosclerosis, and increased progression of hypertension." (PMID 20037727, 2009). "MMP9 exacerbates atherosclerosis, myocardial fibrosis, cardiac injury by extracellular matrix degrade and autophagy inhibition, as well as plays a pivotal role in the progression of various diseases, serving as an important target for the treatment of cardiovascular disease." (PMID 40630623, 2025). "In the current study, ATO and BA significantly decreased the level of MCP-1 (p < 0.01), VCAM-1 (p < 0.01) and MMP9 (p < 0.05), indicating that BA may play a positive role in preventing the formation and development of atherosclerosis." (PMID 40529499, 2025). "In atherosclerosis models, high-dose omega-3 regimens stabilize plaques and blunt inflammatory remodeling; findings consistent with a reduction in protease-driven matrix degradation (with MMP-9 a recognized contributor to plaque vulnerability)." (PMID 41304763, 2025). "A bioinformatic analysis and machine learning algorithms approach illustrated that 5 hub genes (SPI1, MMP9, C1QA, CX3CR1, MNDA) could predict the risk of atherosclerosis in SLE." (PMID 40725777, 2025). "Consequently, MMP-9 has the potential to work not only as a marker of plaque vulnerability but also as a potential target for the treatment and management of atherosclerosis and its complications." (PMID 40364266, 2025). "MMP9 may contribute to the initiation of atherosclerosis and may be a potential biomarker for the early identification of atherosclerosis in patients with diabetes." (PMID 38660518, 2024). "In addition, VCAM1, NCF2, RAC2, MMP9, and ICAM1 were associated with fluid shear stress and atherosclerosis." (PMID 38640295, 2024).
atherosclerosis (continued). "Neutrophils are key cells that accelerate the progression of atherosclerosis; they can raise the area and instability of plaques by releasing various cytokines and adhesion factors and enhance macrophage phagocytosis of lipids and MMP-9 levels." (PMID 39742022, 2024). "This study found that MMP9 is highly expressed in atherosclerosis." (PMID 37978381, 2023). "The molecular docking results predicted that quercetin and naringenin from Folium Artemisiae argyi could be effective in atherosclerosis therapy by targeting MMP9." (PMID 37880698, 2023). "SMAD3, TNF, MMP2, MMP9, CTGF, CD44 and AKT1 are associated with atherosclerosis." (PMID 37328880, 2023). "The levels of neutrophil-associated plasma proteins, such as MPO and matrix metalloproteinase 9 (MMP-9), could predict the risk of cardiovascular events related to the severity of atherosclerosis." (PMID 37569455, 2023). "Interestingly, MMP-9 is also related to cardiovascular problems like atherosclerosis in CKF individuals." (PMID 37510279, 2023). "The level of MMP-9 also increases rapidly in cardiovascular diseases such as arterial hypertension, atherosclerosis and myocardial infarction, and a significant number of publications on MMP-9 emphasize its importance as an important and useful marker in diagnosis and estimation of prognosis." (PMID 37893149, 2023). "Finally, eight hub genes were identified, and IL-1β, VEGFA, and MMP9 genes in the fluid shear stress and atherosclerosis pathway are the most likely target genes in treating atherosclerosis." (PMID 37880698, 2023). "Genes involved in fluid shear stress and atherosclerosis include IL1β, TNF, MMP9, AKT1, and NOX4; genes associated with AGE-RAGE signaling pathway in diabetic complications include AKT1, IL1β, and NOX4; while genes associated with HIF signaling pathway contain STAT3, NOX4, NFκB, and MAPK1." (PMID 36192741, 2022). "MMP-9 is well recognized for its proteolytic action on extracellular matrix proteins and its involvement in long-term remodeling processes that occur in pathological events such as atherosclerosis and heart failure." (PMID 35407517, 2022). "SMY could reduce aortic plaque area and MMP9 expression in animal models of myocardial ischemia and atherosclerosis (AS) in response to DEP exposure." (PMID 36506810, 2022). "Among MMPs, MMP-9 plays a crucial role in the development of atherosclerosis." (PMID 35449607, 2022). "Therefore, the mitogen-activated protein kinase (MEK)/ERK pathway can promote the development of atherosclerosis by regulating the expression of MMP-9." (PMID 35455042, 2022). "MMP-9 is an important enzyme that degrades the main component of vascular basement membrane (type IV collagen) and is closely related to the occurrence and development of atherosclerosis." (PMID 35075377, 2022). "• In an in vitro study, oleuropein at the dose of 20 μg/ml showed anti-inflammatory activity after 30 min of administration by inhibiting the secretion of tumor necrosis factor alpha (TNF-α)–induced matrix metalloproteinase 9 (MMP-9), which additionally resulted in the anti-atherosclerosis effect." (PMID 35496299, 2022). "A recent study assessing both sexes in a matrix metallopeptidase 9 (MMP-9) overexpression model of atherosclerosis, revealed that both male and female rabbits developed calcified lesions in the aortic arch, with qualitative assessment suggesting greater calcification in males." (PMID 33924852, 2021). "Subsequent studies also proposed that MMP-9 may serve as a predictor of atherosclerosis in patients with type 2 diabetes." (PMID 34211634, 2021). "A single vulnerable plaque may rupture through MMP-mediated disruption of the fibrous cap, but the elevated plasma concentrations (particularly of MMP-9) seen in atherosclerosis may also have important systemic effects." (PMID 34531813, 2021).
atherosclerosis (continued). "Our observation that CaD significantly reduced MMP9 expression and activity corroborates a recent study in a rabbit model of atherosclerosis, in which CaD reduced MMP9 in local vascular walls reducing atherosclerotic plaque formation and improved endothelial function." (PMID 34829669, 2021). "It is suggested that suppressing the production of collagenases, such as MMP-1, MMP-8, MMP-12, and maintaining the activity of MMP-9 which is involved in vascular repair may be a future direction for treating atherosclerosis." (PMID 34026849, 2021). "Thus, one of the important aims of the present study was to examine the possible protective effect of Carvedilol, one of the medications for atherosclerosis, on osteoporosis and to evaluate the effects of this drug on MMP-9 activity." (PMID 34610044, 2021). "Of note, MMP-9 has a dual role in the progression of atherosclerosis." (PMID 34026849, 2021). "Previous studies suggest that MMP-9 is involved in the formation of plaque fibrous caps, which can lead to plaque instability and are closely related to atherosclerosis, the severity of cerebral infarction, cognitive decline, and the prognosis of cerebrovascular disease." (PMID 34260532, 2021). "Matrix metallopeptidase 9 (MMP-9) plays a vital role in atherosclerosis and plaque formation." (PMID 34260532, 2021). "Collectively, our study provides the first evidence that miR-491-5p inhibited the growth and migration of VSMCs by targeting MMP-9, which might provide new biomarkers and potential therapeutic targets for atherosclerosis treatment." (PMID 33313408, 2020). "The expression of MMP-9, which serves as an established marker for inflammation during atherosclerosis progression, shows a strong upregulation in ApoE−/− mice due to high-fat diet induced plaque development after 22 weeks, while control animals only show a low upregulation." (PMID 33255872, 2020). "We first examined whether MMP‐9 overexpression affected the early‐stage lesion formation of atherosclerosis in rabbits fed a cholesterol diet for 16 weeks." (PMID 32126159, 2020). "In the second experiment, rabbits were fed a cholesterol diet for 28 weeks and developed greater and more advanced lesions (than experiment one) which enabled us to examine whether increased MMP‐9 affects the progression of atherosclerosis." (PMID 32126159, 2020). "An experimental study used smooth muscle cells from rat thoracic aorta (A7r5 cell line) to analyze the influence of different exposure times (up to 48 h) and concentrations of DEHP (2, 3.5, 7, 10.5, 14, 17.5 ppm) on matrix metalloproteinase (MMP)-2 and MMP-9, that are related with atherosclerosis." (PMID 32707888, 2020). "All of these effects on the regulation of MMP-9 expression may contribute to the development and progression of atherosclerosis." (PMID 33082709, 2020). "Matrix metalloproteinase‐9 (MMP‐9), or gelatinase B, has been hypothesized to be involved in the progression of atherosclerosis." (PMID 32126159, 2020). "In addition, researchers have observed that in mice knock-out for the MMP9 gene, migration potency of the VSMCs as well as atherosclerosis lesions were reduced in comparison to the wild-type animals." (PMID 32429880, 2020). "Inhibition of MMP-2 and MMP-9 has been employed as a potential strategy to prevent atherosclerosis." (PMID 32908568, 2020). "A previous animal study demonstrated that montelukast inhibited the development of atherosclerosis in association with decreased expression of MMP-2 and MMP-9, and another experimental study indicated that montelukast produced anti-atherogenic effects related to MCP-1 downregulation." (PMID 31263710, 2019). "MMP-2 and MMP-9 are overexpressed in a human myocardial infarction, and the expression of MMP-1 and MMP-3 is associated with a protective effect in the development of atherosclerosis." (PMID 31067818, 2019).